CD4 (CD4 molecule)
Diseases named in the same sentence as CD4 in open-access papers (continued):
Sharing a sentence is not in itself a finding about the gene and the disease.
tumor (continued). "SLPs containing immunogenic CD8 and CD4 tumour epitopes are therefore attractive tools to implement therapeutic cancer vaccine." (PMID 23284752, 2012). "CD4+ T cells augment the antigen-presenting capacity of dendritic cells and promote the expansion of tumor-reactive CTLs." (PMID 24213236, 2012). "In contrast the site of CIITA-transfected tumor cells injection was rapidly infiltrated by CD4+ T cells." (PMID 22849661, 2012). "Depletion of either CD4 or CD8 T cell subsets prior to anti-OX40/IL-2c therapy abrogated the anti-tumor efficacy of the treatment." (PMID 22496812, 2012). "In the tumor, T cells were seen in lamina propria-like parts of the tissue, where CD4+, CD8+ and Tregs were co-localized." (PMID 22319577, 2012). "Tumor growth in the mice treated with anti-CD8 was indistinguishable from that of the mice injected with saline, but tumor growth in the mice treated with anti-CD4 was slightly slower than that of the mice treated with anti-CD8 and injected with saline." (PMID 22348070, 2012). "Elevated levels of PGE2 by tumor cells can directly recruit CD4+CD25+ cells through interactions with their EP2 and/or EP4 receptors, an effect that was blocked using anti-PGE2 antibody." (PMID 23029485, 2012). "In this pilot study, we observed increased levels of recently activated Tregs with tumor migrating ability (CD4+CD25hiFoxp3+CD127−CCR4+CD38+ cells) in patients when compared to controls." (PMID 24213326, 2012). "Induction of anergy in antigen-specific CD4+ T cells is an early event in the course of tumor progression." (PMID 22400040, 2012). "In an effort to further understand the roles of CD8+ and CD4+ T cells in antitumor immunity, tumor tissue samples from DCLV-Null- or DCLV-PSCA-immunized mice were collected, paraffin-embedded, and subjected to staining of nucleus and surface markers." (PMID 23139820, 2012). "Cell types known to mount anti-tumor immune responses against SCC included CD4+ helper T cells (Th) and CD8+ cytolytic T cells (CTL)." (PMID 22558071, 2012). "Consistent with this notion, depletion of CD4+ T cells has been shown to improve vaccine therapeutic efficacy in several preclinical tumor settings." (PMID 23144888, 2012). "We and others show that tumor-antigen recognition is accompanied with induction of both CD4+ effector cells and Tregs." (PMID 22400040, 2012). "Elevated numbers of CD4 Treg cells have been found to enhance tumor progression and poor survival in various hematological (including MM) and non-hematological malignancies." (PMID 23152910, 2012). "The mean fluorescence intensity (MFI) showed that Treg had more CTLA-4 per cell than conventional CD4+ T cells, both in the tumor and in the unaffected tissue." (PMID 22319577, 2012). "In parallel, frequencies of activated CD4+ conventional T cells with a Th1 profile were decreased in the tumor, while granzyme B+ putative cytotoxic CD8+ cells were present." (PMID 22319577, 2012). "We took advantage of the ex-vivo re-stimulation assay developed in our laboratory to test the presence and the quality (i.e., the cytokine profile) of anti-viral and anti-tumor recall CD4+ T cell responses in healthy donors and neoplastic patients." (PMID 22879946, 2012). "In the meanwhile, CD4 helper T cells have gained interest in anti-tumour immunity and immunotherapy." (PMID 23284752, 2012). "The accumulation of CD4+CD25+ Tregs can result in tumor growth through the suppression of anticancer immunity." (PMID 22827934, 2012). "Immature dendritic cells are also recruited to the site, where they engulf necrotic and apoptotic tumor cells and present tumor-associated antigen (TAA) epitopes on MHC class II receptors to naïve CD4+ T cells." (PMID 23029485, 2012). "While previous vaccine efforts have focused exclusively on HLA class I-restricted peptides, class II-restricted peptides are necessary to induce CD4+ helper T cells and sustain effective anti-tumor immunity." (PMID 23186108, 2012).
tumor (continued). "This was compatible with immunohistochemical findings of CD4 positivity of tumor cells and scatter normal lymphocytes at the background in the tissue block." (PMID 23006414, 2012). "Tumor infiltrating CD4+ Th lymphocytes can support an effective host anti-tumor immune response against sporadic CRC." (PMID 23109839, 2012). "Presence of CD4+ T cells in the tumor positively correlated with tumor-specific immune responses that developed following combined therapy." (PMID 23233905, 2012). "As a consequence, the granzyme-highly expressing CD4+ T cells exhibited a strong cytotoxic activity that restricted tumor development." (PMID 23145026, 2012). "Earlier studies have highlighted the importance of CXCR3 ligands in recruiting NK cells, as well as CD4+ or CD8+ T lymphocytes to the tumor site." (PMID 22333315, 2012). "In contrast to the known anti-tumor effector functions mediated by tumor antigen-specific T cells, regulatory T (Treg) cells, consisting of a subpopulation of CD4+ T cells, are known to be involved in the establishment and growth of tumor cells." (PMID 23028615, 2012). "It has been found that CD4+ T lymphocytes can promote metastasis by activating the EGFR signaling pathway in a Th2-type tumor microenvironment." (PMID 22420471, 2012). "The expression profiles of the main CD4+CD8+CD69− population of thymic tumour cells present in the thymus of the A238L transgenic mice were compared to the same cell populations from wild type and mutA238L mice." (PMID 22558084, 2012). "CD4+ T cells augment the antigen-presenting capacity of DCs and promote the expansion of tumor-reactive CTLs." (PMID 24213236, 2012). "In summary, with an arsenal of diverse cancer-fighting weapons, CD4+ T cells can mediate tumor destruction either on their own or by cooperating with other immune cells." (PMID 22400040, 2012). "Neither transfer offered a significant delay in tumour growth, although CD4+ T cells did delay the tumour onset by a few days, but then all mice succumbed to tumours." (PMID 22506061, 2012). "In ductal cancers increased CD4+ and FOXP3+ TIL numbers are associated with more aggressive tumor features." (PMID 22471961, 2012). "There was a pronounced reduction in the percentage and absolute number of OT-II CD4+FoxP3.gfp+ T cells harvested from the spleen, tumor-draining lymph nodes, and tumor of mice treated with SA-4-1BBL as compared with untreated controls." (PMID 22870329, 2012). "In contrast, increase tumor densities of Tregs, measured by surface markers CD4 and CD25 plus intracellular FoxP3, as compared to TM40D control, suggestive of a shift of the Treg population from the circulation to the primary tumor." (PMID 23029485, 2012). "There was an almost complete demethylation of the FOXP3 promoter in the CD4+FOXP3+ cells from both the tumor and unaffected tissue, indicating that they stably express FOXP3." (PMID 22319577, 2012). "In murine models, selective elimination of Treg cells (i.e., CD4 + CD25 + FOXP3+) restores an effective anti-tumor immune response leading to tumor regression." (PMID 22383042, 2012). "To characterize further the alpha-beta-T cell subtype responsible for the promotion of tumor growth, we analyzed tumor growth in CD4−/− and CD8−/− mice." (PMID 22880059, 2012). "These analyses demonstrated that lymphocytes infiltrating the tumor consisted mainly of CD4+ T cells with only few CD8+ T cells at the periphery of the tumor tissue." (PMID 22674057, 2012). "The role of CD4+ T lymphocytes in immunity to virus-induced tumours has been less studied, but it is thought to provide help for MHC-class I-restricted CD8+ cytotoxic (antitumour) T lymphocytes." (PMID 22489251, 2012). "Administration of the triple combination caused dramatic recruitment of CD8 T lymphocytes and NK cells into the tumor area, as well as slight recruitment of CD4 T lymphocytes." (PMID 22295090, 2012).
tumor (continued). "Id-specific TCR-transgenic mice are protected against MOPC315 tumors, and the primary anti-tumor immune response in these mice is mediated by the Id-specific TCR- transgenic CD4+ T cells." (PMID 23144743, 2012). "Tumor-exosomes can inhibit lymphocyte, predominantly CD4+ T cell proliferation in response to IL2, which is accompanied by impaired CD25 up-regulation and stronger suppressive activity of regulatory T cells (Treg), possibly due to exosome-associated TGFβ1." (PMID 23190502, 2012). "The cancer relevance of these CD4+ T cells were further underlined, since IDO-reacting T cells in addition react toward DC pulsed with IDO+ tumor lysates." (PMID 22388712, 2012). "While adoptive transfer of anti-tumor CD4+ T cells can be efficacious, expansion of anti-tumor CD8+ T cells is also an important goal, particularly in light of the association between their persistence and clinical responses." (PMID 22279573, 2012). "In contrast, tumors in the groups with depletion of either CD8+ or CD4+ T cells developed a faster rate of tumor growth, although some tumor-protective effect remained." (PMID 23139820, 2012). "Consistent with the in vitro data, immunomodulation with SA-4-1BBL blocks the conversion of conventional CD4+ T cells into iTreg cells in a tumor setting in vivo." (PMID 22870329, 2012). "Several studies indicate that these CD8+ Treg target responding CD4+ T cells to inhibit their induction of macrophage-dependent delayed type hypersensitivity (DTH) responses to tumor antigens (Ags)." (PMID 23060881, 2012). "Compared with the non-tumor-bearing group, the percentages of CD3+ T lymphocytes, CD4+ T lymphocytes and the CD4+/CD8+ ratio of tumor-bearing rats were significantly lower before operation (P<0.05)." (PMID 23139816, 2012). "Later a three-component GLP vaccine by Ingale and coworkers (a three palmitic acid Pam3CSK4 moiety, a CD4+ and a B-cell epitope) showed induction of strong tumor-specific IgG responses." (PMID 22815882, 2012). "Still, the ratio of CD8+Granzyme B+ cells to CD4+CD25hi Treg cells was higher in the unaffected then the tumor mucosa." (PMID 22319577, 2012). "CD4+ Th1 lymphocytes expressing CXCR3 have been shown to be important for anti-tumor responses, and the reduction in CXCR3+ cells probably mirrors a reduction of Th1 cells and CD8+ CTL in the tumor area." (PMID 22319577, 2012). "CD4+ T cells are required for activation of tumour-specific cytotoxic CD8+ T cells, but they can also eradicate cancer in the absence of CD8+ T cells." (PMID 22649466, 2012). "These tumor migrating CCR4+ CD4+ T cell effector subsets, however, were found at similar levels between patients and controls." (PMID 24213326, 2012). "We have recently shown that IFN-γ produced by Id-specific CD4+ T cells render macrophages directly cytotoxic to cancer cells and thereby tumor protection." (PMID 23144743, 2012). "Accordingly, TCR-transgenic mice with large tumors (T), had significantly reduced numbers of Id-specific (GB113 positive) DP (CD4+CD8+) and SP CD4+ thymocytes compared to tumor-free (TF) as well as unchallenged (UC) mice." (PMID 23144743, 2012). "Immunohistochemical analysis for tumor tissue after HSV-tk/GCV treatment showed a great quantity of CD4+, CD8+ lympholeukocyte recruiment." (PMID 22971726, 2012). "Target antigens should be widely expressed in tumour cells, and able to induce robust CD8 and CD4 anti-tumour T cell responses." (PMID 23284752, 2012). "To further investigate the role of CD4 T cells in our model we wanted to determine if increasing the number of tumor-specific CD4 T cells would enhance tumor regression and or maintain the tumors in check for longer." (PMID 22911764, 2012). "Spontaneous recognition of tumour cells by CD4 T cell clones depends on the nature of the antigen and on its subcellular localization." (PMID 23284752, 2012).
tumor (continued). "This review focuses on the latest progresses regarding the impact of chemotherapy on CD4+ T-cell phenotype and function and discusses the prospect of exploiting CD4+ T cells to control tumor progression and prevent relapse after chemotherapy." (PMID 22400040, 2012). "Third, CD4+ T cells are also cytotoxic directly against tumor cells, although the tumor cells that we evaluated here lack MHC II (unpublished results)." (PMID 22397502, 2012). "TH cells were crucial for the establishment of what we defined as “therapy induced anti-tumor vaccination” because naive mice depleted of CD4+ TH cells were unable to reject primary tumors after L19mTNFα/melphalan treatment." (PMID 22849661, 2012). "Further, several murine tumor models have demonstrated that CD4+ T cells are required for an effective anti-tumor immune response." (PMID 22563434, 2012). "On the other hand, integrin αEβ7, that serves to attach lymphocytes to E-cadherin on epithelial cells, but also has been implicated in Treg function, was expressed by more CD4+ tumor infiltrating T cells than CD4+ T cells in unaffected mucosa (p<0.05)." (PMID 22319577, 2012). "These cells have been found in the tumor milieu and mediate immunosuppression by secreting immunosuppressive interleukin-10, decreasing CD4+ and CD8+ T-cell viability, and attracting Treg." (PMID 23056925, 2012). "Accordingly, in the AOM + DSS mouse model, Becker and colleagues demonstrate that IL-6 is highly produced by CD4+ T cells and promotes tumor cell proliferation via STAT3 activation." (PMID 23109839, 2012). "Flow cytometric analyses of CD45.2+ TILs revealed a decrease in the percentage of CD4+CD25+Foxp3+ Tregs in tumor infiltrates from vaccinated mice versus controls." (PMID 22860107, 2012). "In analysis of the mechanisms underlying the protective effect, we showed that the vaccination was followed by enhanced accumulation of tumor-infiltrating lymphocytes (TILs) with enrichment of conventional CD4+ T cells but reduced representation of Treg cells." (PMID 23071764, 2012). "The percentage of Treg cells (CD4+Foxp3+T cells) in the tumor microenvironment was similar at different time points." (PMID 23140567, 2012). "In contrast, CD4+ depletion in combination with Fc-mGITRL treatment results in the same percent tumor regression as CD4+ depletion alone." (PMID 22654588, 2012). "Tumor-specific CD4+ T cells are subject to a variety of tolerizing mechanisms operative in the tumor microenvironment." (PMID 22400040, 2012). "Still, the ratio of CD8+Granzyme B+ cells to CD4+CD25hi Treg cells was significantly higher (p<0.01) in the unaffected then the tumor mucosa." (PMID 22319577, 2012). "In vivo, tumor cells secrete chemoattractants such as MCP-1 which play an important role in the host antitumor immune response by recruiting CD4+ and CD8+ cells." (PMID 22496835, 2012). "Knowledge of antigen-specific CD4+ T cells frequencies is pivotal to the choice of the antigen to be used in anti-viral and anti-tumor vaccination procedures and for monitoring of immune responses." (PMID 22879946, 2012). "The high quantity and quality of vaccine-induced CD4+ T-cell responses have several implications for tumor immunotherapy." (PMID 22397502, 2012). "As an alternative strategy, 8 frozen tumor sections from mice in each treatment group were processed for dual immunohistochemistry, staining for the caspase-3 apoptosis marker and CD4 or CD8 T cell markers." (PMID 22159900, 2012). "The activation of dendritic cells promotes the induction of an adaptive immune response, through tumor antigen (Ag) presentation to CD8 cytotoxic T cells (CTL) with help from CD4 cells, ideally generating a long-lasting immune response." (PMID 22924051, 2012). "Meanwhile, treatment with soluble GITRL induced a decrease in the suppression mediated by the activated tumor-infiltrating Tregs and restores the proliferative capacity and cytokine production of CD4+CD25− T cells." (PMID 23251213, 2012).
tumor (continued). "Granzyme B is a well-known cytolytic molecule found in specific granules of CD8+ and CD4+ CTLs as well as in NK cells; it also lyses tumor cells and virus-infected cells." (PMID 23300563, 2012). "The percentages of CD4+CD25+Foxp3+ Treg cells infiltrated in tumor sites were dramatically decreased after WGP treatment, and were again reversed to high levels after GITR blocking treatment." (PMID 23077535, 2012). "High efficiency of targeting tumor antigen to DEC+ DCs allows a significantly lower dose of protein to achieve potent CD4+ and CD8+ T-cell responses." (PMID 22397502, 2012). "Taken together, these results demonstrate that immunomodulation with SA-4-1BBL is effective in preventing the conversion of conventional CD4+ T cells into CD4+CD25+FoxP3+ T cells in a tumor microenvironment." (PMID 22870329, 2012). "In a pilot study on 15 patients treated with anti-CTLA-4 Tremelimumab, clinical response was also associated with increased tumor infiltration by CD8+ TIL and a variable association with CD4+ TIL." (PMID 23284620, 2012). "As most tumor-associated antigens are derived from a mutated form of self and since T-regs play a key role in maintaining self-tolerance, we analyzed whether or not vaccination with either full-length or epitope encoded Mam-A DNA induced higher numbers of T-regs (CD4+CD25+FoxP3+)." (PMID 22911764, 2012). "Particularly, the CD4+CD25+high regulatory T cells (Treg) derived from naturally existing Treg cells or mostly converted from peripheral naive CD4+ T cells are considered to play a crucial role in tumor immunotolerance." (PMID 22722448, 2012). "In recent years, we have described spontaneous CD8+ as well as CD4+ T-cell reactivity against IDO in the tumor microenvironment of different cancer patients as well as in the peripheral blood of both cancer patients and to a lesser extent in healthy donors." (PMID 22388712, 2012). "With the exception of macrophages (Mφ) (CD11b+) and DC (CD11c+), which most efficiently took-up tumor-exosomes, uptake by CD4+, CD8+ and sIgM+ lymphocytes was in a comparable range and uptake by granulocytes was lower." (PMID 23190502, 2012). "Tumor infiltrating immune cells such as CD4+, CD8+ and FOXP3+ T-cells and macrophages secrete soluble effector molecules such as interferons, IL-6 and TNF, and some of these can directly influence innate immune gene expression in keratinocytes." (PMID 22808251, 2012). "Analysis of Treg subsets revealed a Cy-sensitive CD4+Foxp3+CD25low tumor-seeking migratory phenotype, characteristic of effector/memory Tregs, and capable of high avidity T cell suppression." (PMID 22359647, 2012). "Particularly relevant in this study, NFAT4 KO mice developed tumours with immature CD4+CD8+ DP thymocytes." (PMID 22558084, 2012). "nTReg cells derived from thymus are considered as classic TReg cells, by contrast, iTReg cells develop in the periphery in response to self- or tumor antigens by converting naive CD4+ T cells into TReg cells." (PMID 22481922, 2012). "Consistent with this, IL-17A-deficient C57/Bl6 mice are characterized by a reduced Stat3 activation, as well as increased numbers of tumor infiltrating CD4+ and CD8+ T cells, which produce higher amounts of IFN-γ as compared to wild-type littermates." (PMID 22855687, 2012). "They obtained strong response rates and were able to demonstrate the involvement of CD4+ T cells in controlling the primary tumor site and the role of CD8+ T cells in controlling distant tumors." (PMID 22400032, 2012). "A low proportion of CD4+ cells appears also to be significantly related to EBV status, probably due to the relation with the local tumor-associated suppression of EBV-specific T-cell responses observed in EBV+ HL cases." (PMID 22927872, 2012). "This was accompanied by decreased levels of IL-6 and TGF-β, increased numbers of IFN-γ and TNF-α producing CD4+ T cells as well as a significant reduction of tumor growth." (PMID 22855687, 2012).